LCN2 (lipocalin 2)
Diseases named in the same sentence as LCN2 in open-access papers (continued):
Sharing a sentence is not in itself a finding about the gene and the disease.
tumor (continued). "In PRAD, LCN2 expression negatively correlated with tumor purity(r = −0.39, P = 1.38e-16) and positively correlated with CD4+ T cells (r = 0.288, P = 2.62e-09), macrophages (r = 0.114, P = 2.00e-02), neutrophils (r = 0.275, P = 1.20e-08), and dendritic cells (r = 0.142, P = 3.82e-03)." (PMID 33425761, 2020). "Moreover, LCN2 modulates the degradation, allosteric events, and enzymatic activity of matrix metalloprotease-9, a metalloprotease that promotes tumor cell invasion and metastasis." (PMID 32575507, 2020). "LCN2 was positively correlated with tumor purity and negatively correlated with TIICs." (PMID 33425761, 2020). "In particular, tumor-associated macrophages (TAM) exhibit an alternative activated and suppressive (M2-like) phenotype and are likely guided by apoptotic cancer cells to release iron, lipocalin 2 and ferritin into the tumor microenvironment." (PMID 32863212, 2020). "The interaction of LCN2 with catechol and iron may explain the advantaged survival of tumor cells in which LCN2 is upregulated." (PMID 32575507, 2020). "In addition, studies have shown that LCN2 can promote the migration and proliferation of tumour cells through kinase signalling pathways." (PMID 33277533, 2020). "Because LCN2’s binding to catechols and iron transport may be essential to tumor cell survival, blocking these interactions is a potential therapeutic target for inhibiting cancer progression." (PMID 32575507, 2020). "Therefore, our research shed light on understanding the latent role of LCN2 in tumor immunology and its use as a prognostic biomarker of cancers." (PMID 33425761, 2020). "Moreover, when murine tumor cells expressing LCN2 were implanted in LCN2 null mice, tumor growth was delayed and survival increased suggesting that expression in stromal cells within the tumor microenvironment is important for progression." (PMID 32328462, 2020). "Moreover, apoptotic tumor cells stimulate expression of lipocalin-2 in macrophages and polarization of these macrophages to M2 phenotypes." (PMID 33679721, 2020). "Moreover, PP2, a specific SFKs inhibitor mainly targeting Lck/Fyn and displaying anticancer activity, abrogated the migration of CXCL1/LCN2 stimulated tumor cells." (PMID 31500632, 2019). "Lcn2-positive cells were observed in peri-tumor areas of liver metastases." (PMID 30841919, 2019). "But data are limited for Lcn2 tumor tissue expression and the observed changes in our present study might reflect culturing artefacts, as Lcn2 is also involved in inflammation and wound healing processes." (PMID 31413815, 2019). "Thus, the multiple sources of LCN2 in the tumoral liver suggests that LCN2 is indeed pleiotropic, possibly participating in multiple functions in the tumor microenvironment, such as damage response, immunity and differentiation." (PMID 30893876, 2019). "In this regard, it will be important for future studies to evaluate whether LCN2 is necessary and/or sufficient for promoting a tumor-supportive state within the premetastatic niche." (PMID 31105883, 2019). "Furthermore, our work demonstrates that both increased CXCL1 and LCN2 in the tumor microenvironment confers a more aggressive phenotype upon cancer cells via the activation of Src family kinases." (PMID 31500632, 2019). "For example, decapping enzyme Nudt3, a member of nudix hydrolase superfamily, promoting MCF7 cell migration and proliferation by modulating β6 and lipocalin-2 mRNA stability; Dcp2, the first discovered decapping enzyme, enhanced tumor cell growth by affected RAS and MYC mRNA stability." (PMID 31164795, 2019). "Taken together, our results provide mechanistic insights into the interaction between PCa cells, stromal cells, and innate immune cells in tumor microenvironment and highlight the role of CXCL1 and LCN2 in a tumor-stroma paracrine axis in promoting cancer-cell aggressiveness." (PMID 31500632, 2019).
tumor (continued). "The identification of recently acknowledged new iron-regulated genes, such as lipocalin-2 (Lcn-2) as well as siderophore-binding proteins, might help to understand how the tumor exploits systemic and local iron management." (PMID 30641920, 2019). "CHI3L1 and LCN2 levels in spleens corroborated the increased splenomegaly at 3 and 6 w p.i. in the 4T1- compared to the Py230-based intraductal model and further indicated the presence of enhanced leukocyte reactions in the 4T1 tumor-bearing mice." (PMID 31921184, 2019). "In serum, on the other hand, CHI3L1 and LCN2 were significantly increased at 1, 3, and 6 w p.i. in the 4T1- compared to the Py230-based intraductal model, reflecting the enhanced metastatic progression of 4T1 tumor cells following intraductal inoculation." (PMID 31921184, 2019). "The observed tumor-associated immune responses and the increased metastasis were associated with significantly induced local and systemic levels of MMP-9, VEGF, CHI3L1 and LCN2." (PMID 30111338, 2018). "The paracrine effect of TCF7L1 on cell migration in vitro and wound closure in vivo suggested that the secreted LCN2 might be a prime effector of TCF7L1 in skin tumorigenesis." (PMID 28467300, 2017). "In addition, LCN2, which is involved in the cell differentiation and tumor invasion of ESCC, is up-regulated by IL-1β." (PMID 28410227, 2017). "Since LCN2 has been shown to stimulate neutrophil chemotaxis in vitro, and inflammation facilitates tumor growth, we evaluated whether overexpressing TCF7L1 increases neutrophil infiltration in tumors and whether downregulating LCN2 alters their infiltration." (PMID 28467300, 2017). "In the tumor context, macrophages may be forced by S1P to upregulate a so far unappreciated iron export system, the key component being Lcn-2." (PMID 28979267, 2017). "Finally, we identified the secreted protein LCN2 as the downstream effector of TCF7L1 that stimulates tumor growth." (PMID 28467300, 2017). "We substantiated Lcn-2 as a key macrophage phenotype determinant, with parallel actions during physiological tissue regeneration and repair mechanisms, but also under pathophysiological conditions such as tumor development." (PMID 28979267, 2017). "Moreover, wild-type and LCN2 knockout tumor cell transplantation experiments pointed to the tumor stroma in generating LCN2 in promoting lymphangiogenesis." (PMID 28804221, 2017). "Importantly, downregulating LCN2 decreased tumor size, abrogating the effect of TCF7L1 overexpression on tumor growth." (PMID 28467300, 2017). "However, lipid mediators such as sphingosine-1-phosphate, released form apoptotic tumor cells, upregulate lipocalin-2 (Lcn-2) in macrophages." (PMID 28979267, 2017). "It has been reported that LCN2 inhibits tumor metastasis/invasion in diverse cancers." (PMID 27912767, 2016). "The immunosuppressive role of LCN2 has also been suggested to facilitate tumor growth." (PMID 27136530, 2016). "In the xenograft model, overexpression of LCN2 significantly promoted tumor growth." (PMID 27602760, 2016). "We have also found that overexpression of LCN2 promotes tumor growth in nude mice." (PMID 27602760, 2016). "Furthermore, LCN-2 protein overexpression was positively correlated with MMP-9 protein up-regulation in the tumor tissue and serum of LST patients (former rs = 0.631, P = 0.000; latter rs = 0.815, P = 0.000)." (PMID 27339395, 2016). "Importantly, inflammatory and ECM related proteins characteristic of adipose tissue from obese subjects, such as osteopontin (OPN), chitinase-3 like-1 (YKL-40), tenascin C (TNC) and lipocalin-2 (LCN-2), have also been directly implicated in tumor growth." (PMID 27612200, 2016). "Taken together, these data confirm the ability of LCN2 to accelerate tumor cell migration." (PMID 26840566, 2016). "Overexpression of LCN2 enhanced tumor cell migration and invasion both in vitro and in vivo." (PMID 26840566, 2016).
tumor (continued). "Conversely, knockdown or neutralization of LCN2 reduced tumor cell migration and invasion." (PMID 26840566, 2016). "Moreover, we observed T3-induced cancer cell invasion and LCN2 expression in vivo, supporting the theory that T3 influences tumor motility via LCN2 regulation." (PMID 25940797, 2015). "Data from the transwell assay showed that after depletion of LCN2 in J7 or HepG2-TRα1 cells, migration abilities were decreased, compared with those of control cells, confirming the ability of LCN2 to accelerate tumor cell migration in vitro." (PMID 25940797, 2015). "In view of our finding that expression of E-cadherin is decreased in LCN2-overexpressing cells, compared with controls, and conversely rescued in LCN2-depleted cells, we propose that LCN2 accelerates tumor cell migration through alterations in E-cadherin expression." (PMID 25940797, 2015). "We propose that LCN2 regulates tumor cell migration through activation of the Met/FAK cascade." (PMID 25940797, 2015). "While it was still unclear whether Lcn2 protein increased in hypoxic tumors, previous studies reported that LCN2 promotes tumor metastasis and that levels of LCN2 protein in the urine increase depending on the tumor stage in breast cancer." (PMID 25467539, 2014). "It is possible that tumor size might be involved in the increased plasma concentration of LCN2 because hypoxic regions increase with tumor size." (PMID 25467539, 2014). "The levels of LCN2 have also been shown to be elevated by several orders of magnitude during injury, infection and malignancy, indicating a role it may play in tumor development." (PMID 24939880, 2014). "Additionally, we confirmed that LCN2 mRNA levels increased in HIF-positive regions in tumor tissues and in cultured tumor cells under hypoxic conditions." (PMID 25467539, 2014). "Expression of mRNA for Lcn2, Mmp9, Bdh2, 24p3R, megalin (another receptor mediating cellular uptake of lipocalin-2), and transferrin receptor (Tfrc) were determined in each tumor and reported as mean of all tumors/tissue samples in each of the four groups of mice." (PMID 22737251, 2012). "The first report, where tumor development was driven by the ErbB2 oncogene, showed both faster onset of tumor genesis, higher primary tumor numbers, larger volume of primary tumors, as well as a higher number of metastases and larger volume of metastases in lipocalin-2 expressing mice." (PMID 22737251, 2012). "Thus, it seems that the largest effect of lipocalin-2 on tumor development and aggressiveness is observed in the mouse model with the slowest onset of tumor genesis, the ErbB2 mouse." (PMID 22737251, 2012). "Yet another explanation could be that lipocalin-2 cannot be utilized properly by the tumor cells in our mouse system." (PMID 22737251, 2012). "We do, however, consider it unlikely that the effect of lipocalin-2 diminishes with the aggressiveness of the tumors if lipocalin-2 promotes tumor growth by offering iron for cell division, as such effect would not be overruled by a strong intrinsic drive for cell division and metastasis." (PMID 22737251, 2012). "In addition, we performed zymography of mouse plasma and tumor extracts from wild type and Lcn2 knock-out mice." (PMID 22737251, 2012). "In light of the present findings, it is tempting to speculate that Lipocalin 2 expression levels correlate with tumor progression because of the concomitant upregulation of the UPR." (PMID 21649922, 2011). "Lipocalin 2, an iron binding protein, is abnormally expressed in some malignant human cancers and may play an important role in tumor metastasis." (PMID 19077278, 2008). "Additionally, the critical role of LCN2 in NETs suggests that E2F5 may further enhance NETs’ tumor-promoting effects by regulating LCN2." (PMID 41488283, 2026).
tumor (continued). "In conclusion, our findings reveal that tumor-derived LCN2 orchestrates a brain-specific metastatic program through dual mechanisms: a paracrine loop involving astrocyte activation and macrophage recruitment and a tumor-intrinsic angiogenic pathway via SLC22A17–JAK2–STAT3–VEGF-A signaling." (PMID 41436606, 2025). "Thus, we assessed whether our Herceptin-conjugated liposomal formulation encapsulating siRNA against LCN2 could be effectively internalized and disrupt the formation of tumor emboli." (PMID 40732340, 2025). "Furthermore, coculture of macrophages with tumor cells increased LCN2 protein levels, an effect that was abolished by the IL-1R antagonist anakinra, indicating that IL-1β–IL-1R signaling mediates macrophage-induced LCN2 upregulation." (PMID 41436606, 2025). "Importantly, using a transwell co-culture system that prevents direct cell–cell contact, we observed that OMFs exposed to EGFRvIII-overexpressing OSCC cells exhibited significantly increased LCN2 levels, supporting a paracrine mechanism of LCN2-mediated tumor–stroma communication." (PMID 40472740, 2025). "However, the roles of LCN2 in tumorigenesis, progression, and metastasis vary from tumor to tumor." (PMID 40109857, 2025). "Therefore, LCN2 can inhibit dedifferentiation during tumor progression." (PMID 40109857, 2025). "Interestingly, some studies demonstrated that LCN2 contributes to inhibiting tumor development." (PMID 40313933, 2025). "Moreover, studies indicate that LCN2 induced ferroptosis is closely related to tumor progression." (PMID 39931061, 2025). "Interestingly, melittin-triggered tumor impediment and cisplatin sensitivity could be abrogated by the overexpression of lipocalin-2 (LCN2), a gene of the IL-17 signaling pathway." (PMID 38318188, 2024). "Collectively, these results indicate that elevated LCN2 stimulates the activation of astrocytes, leading to neuroinflammation and an enhanced release of pro-inflammatory cytokines and chemokines, which can be exploited by tumor cells to promote metastases formation and growth in brain metastasis." (PMID 39188682, 2024). "Also, in other cancer types, Lcn-2 was reported to promote tumor progression." (PMID 37958332, 2023). "Also, studies revealed that LCN2, a ferroptosis related protein, could promote tumor proliferation and adhesion through ferroptosis." (PMID 37487008, 2023). "In addition, we clarified the molecular mechanism of LCN2 functions in tumor-infiltrating T cells." (PMID 38072118, 2023). "Increased expression of LCN2 by metastatic cells in the CSF microenvironment thus may serve a dual role of helping to scavenge limited amounts of available iron from CSF and sequestering it within tumor cells to prevent ferroptotic cell death." (PMID 37878712, 2023). "Consequently, fecal lipocalin-2 levels may become a valuable parameter not only for tumor progression, but also for treatment efficacy." (PMID 37189804, 2023). "In addition to iron regulation, bacteriostasis, and epithelial–mesenchymal transition regulation, we found that LCN2 damaged the antitumor immunity and promoted cholesterol metabolism in T cells, which may be beneficial to tumor metastasis." (PMID 38072118, 2023). "Additionally, SERPINA3 and LCN2 suppress BPCa cell proliferation in an autocrine manner, suggesting that they may act as tumor suppressors in bone metastatic PCa." (PMID 37408474, 2023). "Therefore, we investigated whether LCN2, LOXL2, and MMP9 are interrelated in ECM remodelling, and whether LCN2/LOXL2/MMP9 form a complex to play a synergistic role in tumour progression." (PMID 37753805, 2023). "Overall, these results suggested that SERPINA3 and LCN2 might act as tumor suppressors in PCa." (PMID 37408474, 2023). "In summary, whether the effects of tumor-induced Lcn2 expression on cancer and cachexia progression are based on direct changes in EC function, angiocrine signaling, and vascular integrity or indirect changes in VEGF expression and inflammation remains to be determined." (PMID 37222464, 2023).
tumor (continued). "Lcn-2, also known as neutrophil gelatinase-associated lipocalin (NGAL), oncogene 24p3, siderocalin, or uterocalin, is a 25 kDa glycoprotein that was initially discovered as part of the innate immune system, but was later discovered to deliver iron to the fast-growing tumor cells within the TME." (PMID 37958332, 2023). "As LCN2 is known to suppress the PI3K/Akt pathway, LCN2 could be a tumor suppressor in BPCa." (PMID 37408474, 2023). "Similarly, STAT3 activated the secretion of LCN2(lipocalin 2) from N2 neutrophils, which induced mesenchymal-epithelial transition of tumor cells via ERK/KLF4 signaling pathway and thereby facilitating colonization and metastatic outgrowth in lung under the circumstance of nicotine." (PMID 35356244, 2022). "However, it has been reported that tumor progression in other types of cancers is associated with LCN2 high expression rather than low expression, which is inconsistent with our results." (PMID 35705840, 2022). "The Boxplot analysis revealed that LCN2 CG probesets of the promoter region were methylated (median beta value ≥0.6) or partial methylated (0.6 < median beta value <0.2) in most TCGA tumor types, including the cg13518265 probeset that was highly methylated in 30 tumor types." (PMID 36211450, 2022). "Therefore, it can be speculated that FN1 and CLDN7 proteins may mediate tumor progression through the network interaction with LCN2 and MMP9." (PMID 36211450, 2022). "Furthermore, our data indicated that LCN2 is markedly elevated (6-fold vs. primary tumor) in the distant metastatic sites of the spine (p = 0.0001) and bone (0.0001) compared to the primary tumors in addition to the endogenous expression level of control spine and bone tissues of mice." (PMID 34072157, 2021). "These behavioral effects were independent of tumor growth and basic histologic appearance, as tumor mass and key histopathological tumor characteristics (including ragged parenchymal infiltrations, focal necrotic loci, and acute inflammation) were similar between WT and Lcn2-KO mice." (PMID 33824339, 2021). "It is still unknown what roles the LCN2 exerts in the tumor microenvironment, but new studies suggest that its expression strongly correlates with immune cell infiltration; mainly with the infiltration of neutrophils and type T17 helper cell, which was detected across 32 cancer types." (PMID 33799862, 2021). "Based on these observations, coupled with the relationship between LCN2/CTSD on tumor invasion progression, we speculated that the anti-invasive effect of LCN2 on GBM cell may be partly through CTSD expression and possibly involved in another molecular mechanism." (PMID 34062746, 2021). "Since we consistently observe a muscle-sparing effect in tumor-bearing animals devoid of LCN2, we investigated whether this improvement in muscle mass is mediated by improved food intake or through a direct effect of LCN2 on muscle." (PMID 33824339, 2021). "However, preclinical studies reported contradictory, pro- and anti-tumor functions of LCN2 in PDAC." (PMID 34680216, 2021). "However, there is also evidence suggesting that LCN2 could act as a tumor suppressor by inhibiting proliferation and invasion." (PMID 32575507, 2020). "In addition, our results provided insights in the significant role of LCN2 in tumorigenesis and metastasis, providing a potential mechanism that LCN2 expression might modulate tumor immunity, metabolic activity and EMT in cancers." (PMID 33425761, 2020). "Also, it has been reported that p38β could be a critical step in tumor formation through regulation of lipocalin 2 (LCN2) expression, a direct target of Plakophilin 3 (PKP3)." (PMID 33053909, 2020). "In fact, it was speculated that the iron load of Lcn-2 defines pro-tumor characteristics of Lcn-2." (PMID 30641920, 2019).